INS (insulin)
Diseases named in the same sentence as INS in open-access papers (continued):
Sharing a sentence is not in itself a finding about the gene and the disease.
diabetes (continued). "These insights begin to build a profile of an archetypal patient whose feelings of low efficacy and perceived inability to live up to the standards of diabetes management cause them to seek validation in other ways, including harmful weight loss methods such as insulin restriction." (PMID 38041170, 2023). "The long-term T2D remission in this study was associated with a shorter duration of diabetes, lower preoperative fasting glucose and HbA1c, and less use of insulin therapy before surgery, which are known to be associated with a greater β-cell pancreatic function reserve." (PMID 37085634, 2023). "Insufficient insulin in diabetics causes weight loss by reducing lipid synthesis." (PMID 37396152, 2023). "This resistance to insulin is a crucial factor in the development of elevated blood sugar levels, contributing to complications in both small and large blood vessels associated with diabetes." (PMID 38111407, 2023). "Both dominant and recessive mutations in INS can lead to diabetes." (PMID 37283036, 2023). "Participants with central RTH might have higher FT4 levels, thus reducing the risk of hyperglycemia and diabetes by improving glucose utilization and enhancing insulin sensitivity." (PMID 37429739, 2023). "This kind of diabetes is caused when the body’s cells cannot utilize insulin appropriately." (PMID 37958014, 2023). "Taken together, we find a functional interaction between ENPL-1 and ASNA-1 that is necessary to maintain proper insulin secretion in C. elegans and provides insights into how their loss might cause diabetes in mammals." (PMID 36939052, 2023). "Additionally, potential T1D specific risk factors for developing EDs include weight loss at disease onset followed by weight gain caused by insulin treatment, dietary control as part of diabetes management, and intentional insulin omission to control weight." (PMID 36941696, 2023). "Second, previous studies have suggested that the PD may improve insulin sensitivity and prevent diabetes, which could potentially reduce the risk of CRC." (PMID 37468920, 2023). "Chronic exposure to exogenous glucocorticoids is associated with an increased risk of developing type 2 diabetes mellitus, which is mainly due to the detrimental effects of glucocorticoids on insulin-dependent glucose uptake in peripheral tissues, gluconeogenesis and insulin secretion." (PMID 38137336, 2023). "Disruption of insulin sensitivity is associated with diabetes, as well." (PMID 37513524, 2023). "Mutations and translation defects in INS have been associated with diabetes." (PMID 36967805, 2023). "Administration of insulin in such a physiologic manner appears to improve insulin sensitivity, lower HgbA1c, and, in some instances, has been associated with the reversal of end-organ damage that leads to complications of diabetes." (PMID 37446104, 2023). "Additionally, there were great differences in pancreatic islets DNA methylation between genders, and extensive DNA methylation often occurred in women that can lead to increased insulin secretion, reducing the risk of diabetes mellitus." (PMID 37139334, 2023). "Whether the association of type 2 diabetes (T2DM) with dementia was differed by sex remains unclear, and the roles of age at onset of disease, insulin use and diabetes’ complications in their association are unknown." (PMID 36804018, 2023). "Diabetes is a serious metabolic disorder that is caused by a deregulation of blood sugars due to the inefficient production of insulin by the pancreas or when the body is unable to respond and use effectively that insulin." (PMID 38074122, 2023). "Previous studies have shown that insulin directly affects the risk of type 2 diabetes mellitus (T2DM) but the relationship between insulinaemic potential of diet and lifestyle and the T2DM risk is still unknown." (PMID 37394447, 2023).
diabetes (continued). "Therefore, to analyze the influence of the association of diabetes and HFDs on markers of insulin resistance, the expression of transcriptional proteins related to the insulin signaling pathways PI3K/Akt and MAPK (ERK1/2) were evaluated in ovarian homogenates." (PMID 37892483, 2023). "Moreover, the need for more intensive diabetes treatment as a marker of diabetes severity was associated with a greater degree of myocardial fibrosis and LV diastolic dysfunction, especially in insulin-treated diabetic patients." (PMID 36765354, 2023). "By improving glucose and lipid metabolism, glycemic control, insulin sensitivity, and lipid profile, AX supplementation may provide support to individuals at risk of developing not only diabetes but also atherosclerosis and other cardiovascular complications." (PMID 37888449, 2023). "Whether it serves as a marker of heightened diabetes control or due to the associated reduction in glucotoxicity with improved insulin sensitivity, insulin seems to alleviate the uric acid retention associated with THZ." (PMID 38274913, 2023). "Further adjustment for duration of diabetes, insulin therapy, baseline category of risk for foot disease at study enrolment, diabetes distress and depression or any other covariate measured did not materially change the magnitude or statistical inference of results (data not shown)." (PMID 37501178, 2023). "Insulin usage among high-risk patients has the advantage of protecting against glucotoxicity that may lead to diabetes-related microvascular complications." (PMID 37542280, 2023). "In vivo, the e-B cells expressing the antigen-specific construct recognized by pathogenic CD8+ T cells were able to protect against diabetes adoptively transferred by insulin-specific CD8+ T cells into immunodeficient NOD.Scid mice at a high B cell-to-T cell ratio (5:1)." (PMID 37731505, 2023). "However, the relationship between insulin resistance and skeletal muscle is bidirectional: older adults with sarcopenia have an increased risk of developing diabetes, whilst adults with diabetes have an increased risk of sarcopenia." (PMID 37986616, 2023). "Therefore, according to our study, we concluded that, there were some associations between VEGF and insulin in the internal environment of hyperglycemia in diabetes patients." (PMID 36927328, 2023). "We hypothesized that there was a sex-specific association between diabetes and dementia, and early onset T2DM, insulin use and diabetes’ complications might strengthen the risk between diabetes and dementia." (PMID 36804018, 2023). "We conclude that, whilst PAX4 is not essential for in vitro stem cell differentiation to SC-islets, both PAX4 haploinsufficiency and loss-of-function coding alleles increase the risk of developing diabetes by negatively impacting human beta cell development and insulin secretion." (PMID 37777536, 2023). "However, a large portion of cases of SGLT2 inhibitor-associated DKA have occurred in individuals with diabetes who are insulin deficient (11 patients, 37.9% of the cases)." (PMID 37441367, 2023). "Diabetes is caused by a relative or absolute deficiency in insulin secretion in the patient’s body." (PMID 37564986, 2023). "Moreover, METTL3/14 modulates β-cell proliferation and functional maturation during early islet development in neonatal mice, whose depletion is associated with β-cell failure, impaired insulin secretion, and glucose intolerance in the progression of diabetes." (PMID 36830642, 2023). "A growing body of evidence indicates that the development of sAD could indirectly be associated with hyperglycemia/diabetes or decreased insulin function in the brain." (PMID 37443762, 2023). "Notably, accumulating evidence indicates that iron status is perturbed in individuals with diabetes, which is believed to be associated with insulin sensitivity." (PMID 37887373, 2023).
diabetes (continued). "Although the reduction or omission of insulin in patients with type 1 diabetes mellitus and eating disorders is associated with very high morbidity and mortality, evidence-based guidance on its treatment is needed, as standard eating disorder treatment models are not effective." (PMID 36793059, 2023). "Longer diabetes duration and insulin use were associated with a higher risk." (PMID 36701363, 2023). "Therefore, it can be concluded that injection of exogenous insulin after the appearance of insulin resistance can still have a positive effect on the low testosterone status caused by diabetes." (PMID 37900148, 2023). "In addition, in our study, a positive attitude towards insulin pump therapy was associated with lower diabetes distress and depressive symptoms." (PMID 36801976, 2023). "Weight loss may prevent and reverse diabetes and improve blood glucose, insulin sensitivity and comorbidities." (PMID 38136211, 2023). "Vitamin D insufficiency increases the risk of diabetes because it lowers insulin sensitivity, and also raises the risk of obesity and CVD because of its effect on the body’s lipid profile, particularly in terms of the prevalence of dangerously high levels of low-density lipoproteins (LDL)." (PMID 37233176, 2023). "The reduction of insulin-stimulated suppression of plasma NEFA levels in the postprandial state is one of the earliest metabolic dysfunctions detected in patients at high risk of diabetes." (PMID 37451484, 2023). "Earlier bedtime means that the longer the dark period, the longer the high level of melatonin was secreted, and the less insulin was secreted, which may lead to an increased risk of diabetes." (PMID 37310940, 2023). "Interventions that reduce the need for insulin in patients with diabetes may be associated with long-term beneficial outcomes." (PMID 37589043, 2023). "Long term consumption of high glycemic diets, which induce high and recurrent surges in blood glucose and insulin levels, increase the risk of insulin resistance, dyslipidaemia, and the development of cardiovascular disease, non-insulin-dependent diabetes mellitus and certain cancers." (PMID 36875857, 2023). "Monogenic diabetes counts for 1–5% of all diabetes cases and can result from mutations in genes encoding β-cell potassium channels, β-cell glucose-sensor glucokinase, transcription factors, and insulin." (PMID 37048081, 2023). "This is unusual as dominant INS variants most commonly cause permanent diabetes." (PMID 36398453, 2023). "The remaining four cases had inherited the pathogenic variant from their mothers, two of whom (both harboring KCNJ11 variants) were diagnosed with diabetes at 3 months of age and had been treated with insulin until the genetic diagnosis in their children (aged 29 and 35)." (PMID 36398453, 2023). "Furthermore, T2DM (90–95% of all diabetes) is caused by a continual reduction in insulin secretion, which is generally accompanied by insulin resistance." (PMID 37894680, 2023). "In studies of HH, for example, it has been noted that individuals with high iron and overweight are especially prone to diabetes, presumably because their relative insulin deficiency cannot compensate for the insulin resistance of obesity, as well as in individuals with normal insulin reserves." (PMID 36137277, 2023). "PPAR-γ belongs to a family of nuclear receptors that can function as lipid sensors and is a receptor for insulin-sensitizing drugs, with its expression being activated by insulin and nutrition and downregulated by fasting, insulin-deficient diabetes, and inflammation." (PMID 37108229, 2023). "The magnesium content of milk may also improve insulin sensitivity, as demonstrated by the decrease in insulin resistance in overweight adults, which could reduce the risk of type 2 diabetes mellitus and cardiovascular disease." (PMID 37107990, 2023).
diabetes (continued). "Hence, ‘out of control’ was more likely linked to insulin omission, resulting in an understanding of ‘loss of control over the diabetes’, more than the eating behavior." (PMID 36754894, 2023). "The diabetes management model revealed that use of ultra-rapid-acting insulin was associated with 0.2% (2.2 mmol/mol) lower HbA1c compared with use of rapid-acting insulin." (PMID 37160785, 2023). "The proposed mechanisms connecting diabetes and gastric cancer include shared risk factors such as obesity and insulin resistance, as well as Helicobacter pylori infection, salt intake, hyperglycemia, and certain medications like insulin and metformin." (PMID 37654164, 2023). "Performing regular exercise is beneficial for the prevention of diabetes mellitus and its complications, as well as improving immune response, susceptibility to infection, glycemic control, and insulin sensitivity, ultimately increasing the resistance of patients with diabetes to the COVID-19 virus." (PMID 37893490, 2023). "The study also assesses factors associated with HRQOL among diabetes patients on insulin therapy." (PMID 37143082, 2023). "Studies in India and Morocco found that significant increases in HbA1c and insulin levels were associated with longer duration of diabetes, which might be due to a gradual rise in insulin resistance." (PMID 37055503, 2023). "Regarding diabetes-specific risk factors, 94% (n=94) had a diabetes duration longer than five years; HbA1c greater than 7% in 70% (n=70); 62% (n=62) had microvascular complications; 83% (n=83) were on insulin, 2% (n=2) on canagliflozin and 1% (n=1) on pioglitazone." (PMID 36960265, 2023). "Moreover, increased blood sugar levels were previously correlated with poor immunity and the administration of insulin was associated with higher neutrophil activity in diabetes." (PMID 37563596, 2023). "Notably, severe insulin resistance found in a subset of patients with diabetes is highly associated with cardiovascular complications, however, the molecular mechanisms linking insulin action and heart disease are not well understood." (PMID 36707786, 2023). "In addition, a first-degree relative of a patient with T2D has up to a 10-fold increased risk for diabetes development compared to the general population and shows a reduced first- and second-phase insulin release before developing any insulin resistance." (PMID 37432389, 2023). "According to the classical definition, it results mainly either from a deficiency in insulin secretion (type 1 diabetes mellitus [T1D]) and/or from a defect in insulin action, namely insulin resistance affecting liver and peripheral tissues (type 2 diabetes mellitus [T2D])." (PMID 36901966, 2023). "However, in high-risk individuals, such as obese patients with low insulin sensitivity, steroids can lead to hyperglycemia and diabetes mellitus." (PMID 36769807, 2023). "Adrenergic receptors modulate several mechanisms beyond BP and heart rate, including lipolysis or insulin secretion as shown by the association between several of our selected variants and the risk of diabetes and/or the lipid profile consistent with the known effect of the pharmacologic modulators." (PMID 37920183, 2023). "For example, flavonoids may lessen the risk of developing diabetes by maintaining glucose uptake, blood glucose points, and insulin secretion, controlling immune function." (PMID 37241737, 2023). "Top downregulated genes included those previously associated with diabetes and obesity, such as Manf and Creld2 that facilitate protein folding, and Igfbp3 and Igfbp7, two structurally similar proteins that regulate the bioavailability of IGFs and insulin." (PMID 36988733, 2023). "Higher HbA1c levels, longer duration of diabetes, and use of insulin therapy for treatment have been reported to be risk factors for DR, and these may reflect poor glycemic control." (PMID 37239172, 2023).
diabetes (continued). "Collectively, these findings suggested that hepatic FASN deficiency in Mc4r-KO mice suppresses FAO and gluconeogenesis in association with augmentation of insulin signaling, which together may ameliorate diabetes." (PMID 37681411, 2023). "Post-prandial exercise not only reduces blood glucose levels but, perhaps more importantly, is associated with lower amounts of insulin in the bloodstream, thereby reducing a factor that precipitates insulin receptor desensitization and perhaps the development of diabetes." (PMID 37606407, 2023). "Moreover, zinc plays a critical role in insulin synthesis, secretion, and storage, and lower zinc status was known to be associated with a higher diabetes prevalence." (PMID 37892448, 2023). "The relatively low overall PAID scores can be rated as positive because physical activity can be stressful, especially for insulin-treated patients with diabetes, given their risk of hypoglycemia and the higher demands set on diabetes self-management to prevent exercise-induced hypoglycemia." (PMID 36674186, 2023). "As an example, insulin and sulfonylureas, which carry a significantly higher risk for hypoglycemia may be more likely to be deprescribed than other diabetes medications." (PMID 37542226, 2023). "An illustrative approach to mitigate impaired weight reduction due to type 2 diabetes mellitus is choosing anti-diabetes medications that increase insulin sensitivity and promote weight loss and deprioritize use of anti-diabetes medications that increase insulin exposure and promote weight gain." (PMID 37990681, 2023). "Conversely, the administration of D-chiro-Ins has proven to ameliorate several symptoms and metabolic parameters associated with diabetes or insulin resistance, henceforth decreasing insulin requirements and, consequently, the insulin-dependent stimulus on androgen synthesis." (PMID 37111094, 2023). "T2D-associated phenotypes linked to chromosome 15 have been described in a number of linkage studies from other groups, namely in the insulin deficient (AkitaxA/J)F2 mice, carriers of diabetes mutation (BKSxDBA/2)F2 mice, (A/WySnJxCAST/Ei) mice and (NZO/HlLtxNON/Lt) animals." (PMID 36614300, 2023). "Diabetes mellitus (type 1) is characterized by chronic hyperglycemia caused by insufficient insulin secretion, whereas diabetes (type 2) is a metabolic disease resulting from the dynamic interaction between defects in insulin secretion and insulin action." (PMID 36837894, 2023). "This metabolic shift causes the accumulation of intermediary substrates, such as acylcarnitines that could be implied to interfere with insulin sensitivity, causing insulin resistance and the onset of diabetes." (PMID 37264408, 2023). "However, the physiology of glucose homeostasis is complex, and the use of insulin and oral agents corrects only part of the underlying pathophysiology of diabetes." (PMID 37958659, 2023). "However, few studies have used this model of estimated insulin sensitivity to examine associations with dietary factors in diabetes." (PMID 37960272, 2023). "By analyzing trends in changes in glycometabolic variables over a 14-year period, we found that the increased risk of diabetes in the long sleep duration group may be caused by increasing glucose levels accompanied by decreased insulin secretion." (PMID 37109236, 2023). "According to a Canadian study, for individuals who are at a high risk of developing diabetes (prediabetes) or those with newly diagnosed type 2 diabetes, vitamin D supplementation for 6 months significantly increased their peripheral insulin sensitivity and β-cell function." (PMID 36839279, 2023). "Furthermore, they concluded the association between the CD24 and insulin sensitivity, suggesting its possible mechanism for diabetes." (PMID 36900128, 2023). "In addition, in obesity-associated T2D, impaired insulin secretion is considered essential for the onset of diabetes." (PMID 37863964, 2023).